CXCL2 (C-X-C motif chemokine ligand 2)
Diseases named in the same sentence as CXCL2 in open-access papers (continued):
Sharing a sentence is not in itself a finding about the gene and the disease.
colon carcinoma (32 papers, 2012 to 2025). "PTGS2, also called COX-2, has been reported to play a critical role in tumor growth and metastasis in colon cancer and high expressions of CXCL2 and CXCL3 have been associated with tumor metastasis." (PMID 29215599, 2017). "Moreover, the chemokine receptor CXCR-2 and its ligands CXCL-1 and CXCL-2 have been proposed to facilitate the growth of spontaneous and inflammation-associated colon tumors." (PMID 25890501, 2015). "CXCL2 has been reported to promote colon cancer metastasis in vivo, and in vitro stimulation of CXCL2 has been shown to increase colon cancer cell proliferation and migration." (PMID 38097680, 2023). "Another study investigating the role of CXCL2/CXCR2 identified that short hairpin RNA inhibition of CXCL2 reduced the expression of EMT markers in colon cancer cells." (PMID 37509721, 2023). "In inflammation and/or cancer of the colon, the expression of CXCL1 and CXCL2 is increased, which causes the chemotaxis of MDSCs." (PMID 35163326, 2022). "The present study showed that CXCL2 induced robust proliferation and migration, underlining the important role of the CXC chemokines in colon cancer cell biology." (PMID 34115261, 2021). "Next, we examined the functional role of CXCR2 in CT-26 cells by studying the effect of the CXCR2 ligand CXCL2 on CT-26 colon cancer cell proliferation and migration." (PMID 34115261, 2021). "The CXCR2 antagonist, SB225002, dose-dependently decreased CXCL2-induced proliferation and migration of colon cancer cells in vitro." (PMID 34115261, 2021). "Further, there was increased expression of mRNA and protein levels of CXCL2 in colon cancer stem cells, whereas CXCL2 knockdown led to the decreased expression of EMT markers, MMPs, and Gai-2, which consequently promoted tumor initiation and development." (PMID 32936304, 2020). "In our study, CXCL2 was found to be highly expressed and correlated with the survival of patients with colon cancer in GSE41258." (PMID 32337262, 2020). "In our study, the increase of CXCL1 and CXCL2 both in rat model and patients with colon cancer correlates with neutrophil recruitment within tumors." (PMID 29983866, 2018). "The expression of CXCL1 and CXCL2 in human colon tumors has been described and there is a report that CXCL1 is highly expressed in poor invasive tumors." (PMID 29983866, 2018). "We aimed to explore the influence of different secreted CXCL2 from colon cancer cells on tube formation by HUVECs." (PMID 29305742, 2018). "Notably, the CXCR2 ligand CXCL2 can promote the development of colon cancer by binding to CXCR2 58, 59 and remodeling the TME 60-62." (PMID 39247594, 2024). "Moreover, WGP inhibited the expression of the chemokines CXCL1 and CXCL2, which are related to angiogenesis and dysplasia-carcinoma transition processes in colon cancers." (PMID 36713833, 2023). "Moreover, the IL6/JAK/STAT3 pathway has been found to upregulate CXCL1, CXCL2, CXCL3, and CXCL11 in patients with colon cancer, which was associated with prognosis." (PMID 35468892, 2022). "Moreover, challenge with CXCL2 triggered significant colon cancer cell migration in vitro in a dose-dependent manner." (PMID 34115261, 2021). "Notably, CXCL2-evoked colon cancer cell proliferation and migration were dose-dependently attenuated by co-incubation with the CXCR2 antagonist SB225002 (respectively)." (PMID 34115261, 2021). "Interestingly, co-incubation of CT-26 cells with SB225002 abolished CXCL2-induced adhesion of colon cancer cells to vitronectin, fibronectin, collagen IV, laminin I and fibrinogen." (PMID 34115261, 2021). "It was reported that CXCL2 could enhance survival of primary chronic lymphocytic leukemia cells in vitro and differential expression of CXCL2 in colon cancer had impact on metastatic disease and survival." (PMID 23951052, 2013). "Several chemokines such as CXCL1, CXCL12, and CXCL2 as well as CXCL17 were involved in the development, growth, and progression of the colon cancer." (PMID 35607443, 2022).
colon carcinoma (continued). "Chen and colleagues found that CXCL1, CXCL2, and CXCL3 were all highly expressed in colon cancer tissues." (PMID 34269159, 2021). "CXCL1, CXCL2, CXCL3, and CXCL11 were upregulated in patients with colon cancer and significantly correlated with prognosis." (PMID 32337262, 2020). "Our results showed that CXCL1, CXCL2, CXCL3, and CXCL11 were all upregulated in colon cancer compared with healthy tissues, and in the colon cancer group, a high level of CXCL1, CXCL2, CXCL3, and CXCL11 was correlated with better survival in TCGA or GEO." (PMID 32337262, 2020). "Previous reports identified an upregulation in the expression of CXCL2 and CXCL3, promoting cancer stem cell like properties and tumorigenesis in LoVo colon cancer cells in culture." (PMID 31835892, 2019). "Notwithstanding, expression of CXCL2, CXCL3 and CXCL8 is increased in colon cancer compared with normal colon tissue and CXCL2 and CXCL3 expression has been found to be already upregulated in premalignant adenomas." (PMID 30591657, 2018). "We have demonstrated here that colon tumors from rats showed a rise of CXCL1, CXCL2 after LipA treatment." (PMID 29983866, 2018). "The selectin E gene (SELE) was predicted to be downstream regulated by NFκB via such chemokines (CCL8, CXCL2, CXCL3), while previous studies observed that it activates the PI3K/NFκB pathway in colon cancer." (PMID 27078000, 2016). "Genetic downregulation of p38α in AOM/DSS-induced mouse colon tumors reduces tumor growth, which correlates with reduced levels of IL-6, IL-11, CXCL-1 and CXCL-2." (PMID 25890501, 2015). "Moreover, inhibition of CXCR2 dose-dependently decreased CXCL2-triggered migration and proliferation, suggesting that CXCL2 and CXCR2 interactions are operational in murine colon cancer cells." (PMID 34115261, 2021). "Interestingly, co-incubation of CT-26 cells with SB225002 abolished CXCL2-induced adhesion to these ECM proteins, suggesting that CXCL2-CXCR2 interactions activate αV integrins on colon cancer cells facilitating attachment to ECM proteins." (PMID 34115261, 2021). "Notably, it was observed that CXCL2 was markedly upregulated along the incisional line in mice, which help explain the CXCR2-dependent accumulation of colon cancer cells at the peritoneal wounds." (PMID 34115261, 2021). "In addition to CCL2, CXCR2 ligands including CXCL1, CXCL2, CXCL3, and CXCL8 produced by CRC cells and neutrophils themselves were found to be responsible for recruitment of CXCR2+ neutrophils/PMN-MDSCs to colon tumors." (PMID 31681563, 2019).
viral infection (30 papers, 2005 to 2025). "CXCL2 is important for neutrophil recruitment during viral infection, which contributes to pathogen clearance, however, this is also closely related to severe inflammatory tissue damage during viral infections, and the worsening of the immunopathology associated with cytokine storm." (PMID 38396742, 2024). "The viral infection group exhibited significantly increased mRNA levels of IL-6, TNFα, CXCL-2, CXCL-3, CXCL-8/IL-8, and CXCL-10 compared to the NC group." (PMID 40872743, 2025). "The proinflammatory monocytes (cluster 4) expressed a special gene combination, namely, chemokine ligands, interleukins, as well as lncRNAs (e.g., CCL3L1, CCL4, CCL4L2, CXCL2) related to virus infection, inflammation, and pyroptosis." (PMID 39473904, 2024). "The chemokine-to-cytokine-to-chemokine cascade (CXCL2) is an important lethality which is essential for defense during viral infections that establish themselves in tissues." (PMID 36834974, 2023). "In a BCSFB model using human choroid plexus papilloma cells, a viral infection with Echovirus 30 showed an enhanced secretion of Cxcl1, Cxcl2, Cxcl3, and Ccl5." (PMID 32645014, 2020). "Inflammation mediated by viral infections that induce G-CSF enhances CXCL2 release and decreases CXCR4 expression on bone marrow-resident neutrophils, tipping the balance in favor of neutrophil release." (PMID 30791481, 2019). "Induction of CXCL2 and IL-1β by bites was compared to other known inducers of neutrophil influx and to virus infection alone." (PMID 27332734, 2016). "For example, the gene CXCL2 can be influenced by other factors including viral infections." (PMID 37509183, 2023). "Interestingly, viral infection via bite synergistically enhanced CXCL2 and IL-1β expression, and neutrophil influx compared to bite alone." (PMID 34073501, 2021). "Indeed, resident cells at the site of infection produce neutrophil-attracting chemokines, CXCL1 and CXCL2, following other viral infections." (PMID 34073501, 2021). "Furthermore, the capacity of M-Tha to interact with RelAp43 was shown to be crucial for the control of the expression of four genes (IFN, TNF, IL8 and CXCL2) during viral infection." (PMID 28000711, 2016). "Despite the inability of virus infection alone to induce substantial expression of CXCL2 or IL-1β, or Ly6GhiCD11bhiCD45+ neutrophil influx, infection combined with bites induced significantly higher expression and an enhanced neutrophil influx compared to bite alone." (PMID 27332734, 2016). "However, the CXCL2 were significantly upregulated on viral infection in the mid‐aged mouse ECs." (PMID 38098255, 2024). "We found that PMN chemoattractant genes Cxcl2 and another chemokine Cxcl10, had significantly reduced expression in Opn−/− mice compared to WT controls at 4 d.p.i., which may be attributed to milder viral infection in the brain." (PMID 28680095, 2017). "Viral infection induces a variety of proinflammatory cytokines and chemokines including IL-1b, IL-6, TNFa, CCL2, CCL3, CXCL1, CXCL2, CXCL9 and CXCL1034,35." (PMID 38750107, 2024). "Viral infection-primed expression of type I IFNs is sufficient to interfere with production of specific chemokines, such as CXCL1 and CXCL2, resulting in impairment of the neutrophil response during secondary S. pneumoniae infection." (PMID 34061598, 2021). "Among the pro-inflammatory mediators, a significant increase in mRNA for CSF2, CSF3, CXCL2, CXCL5, IL6, IL8, and also IL1 and IL18 was observed 24 h after viral infection." (PMID 23723976, 2013). "In addition, the inflammation‐related molecules such as CXCL2 and CXCL10 were upregulated in the mid‐aged ECs upon viral infection." (PMID 38098255, 2024). "Even though CLEC2.Fc was unable to inhibit virus infection and replication, CLEC2.Fc inhibited the expression of IL‐6, CXCL2, CXCL5, CCL2, and IP‐10 at day 3 and day 5 post‐infection, and the expression of TNF‐α, IFN‐γ, IL‐10, and CXCL1 was also suppressed at day 5 post‐infection (red columns)." (PMID 37211986, 2023).
viral infection (continued). "To explore the effect of SPJ treatment on cytokine expression, we used real‐time PCR and observed that viral infection led to increased expression of cytokines and chemokines, including IL‐6, IL‐1β, TNF‐α, IL‐10, IFN‐α, IFN‐β, and IFN‐γ, as well as CXCL‐2, CXCL‐10, CCL‐2, CCL‐3, and CCL‐5." (PMID 37544014, 2023). "All three lncRNA-mRNA pairs, including lncRNA XLOC-022175 vs CXCL2 (co-upregulated), XLOC-019295 vs IFI6 (co-upregulated), and XLOC-017089 vs CD163 (co-downregulated) exhibited significant changes after virus infection, which coincided with the predicted correlation networks." (PMID 33711920, 2021). "Since CXCL1 and CXCL2/3, acting through CXCR2, are potent neutrophil chemoattractants, we investigated their role in dsRNA-induced lung injury, where dsRNA (Poly IC) is a well-described synthetic agent mimicking acute viral infection." (PMID 15921526, 2005). "Moreover, CXCR2 binding to CXCL2, the structurally related GRO family chemokine produced by macrophages, contributes to lung injury during viral infection, an event crucial for the establishment of pro-inflammatory conditions associated with respiratory disorders." (PMID 34361973, 2021). "In addition, levels of chemokines CXCL2, CXCL8, CXCL20 and CXCL14 were higher in men, which supports the hypothesis that the first stage of male response against a viral infection is typically related to inflammation and Th17 cell differentiation processes." (PMID 33271804, 2020). "Under SAD virus infection, depletion of RelAp43 induced no significant change in transcription of any of these genes but CXCL2, probably because of the strong activation of pathways by SAD that may bypass RelAp43." (PMID 28000711, 2016). "In addition to immunosuppressive molecules, antiviral proteins (such as IFNs) produced during viral infections attenuate initial KC/CXCL-1 and MIP2/CXCL2 responses to secondary pneumococcal challenge, resulting in increased persistence of bacteria and death in mouse models of infection." (PMID 23055935, 2012). "Hierarchical clustering identified a distinctive innate immune signature in bite sites that was dominated by neutrophil-attracting chemokines (CXCL1, CXCL2, CXCL3, and CXCL5) and the cytokines IL-1β and IL-6, which were not significantly induced by virus infection alone." (PMID 27332734, 2016).
ovarian carcinoma (29 papers, 2012 to 2026). A malignant neoplasm originating from the surface ovarian epithelium. "Serum CXCL1 and CXCL2 levels are elevated in ovarian cancer patients and are associated with intratumoral MDSC infiltration." (PMID 29703902, 2018). "Ovarian cancer cells drive tumor-associated macrophage (TAM) development and enhance cholesterol efflux by inducing tumor endothelium to secrete C-X-C motif chemokine 2 (CXCL2)." (PMID 40270603, 2025). "This study was designed to reveal the important role of CXCL2 in platinum resistance in epithelial ovarian cancer (EOC)." (PMID 34474677, 2021). "Among them, the research results of CXCL1 and CXCL2 in epithelial ovarian cancer and other tumors have shown that they are related to the malignant biology of the tumor, and they have higher regression coefficients in the model, which has the most significant impact on the prediction model." (PMID 38509620, 2024). "In addition, the expression of CXCL2 has been shown to be induced by TNF-mediated signaling in ovarian cancer cells." (PMID 33807638, 2021). "In ovarian cancer cells, the CXCL2 expression is dependent on IκBα and IKKβ." (PMID 25790431, 2015). "A primary finding of this study is that CXCR2-driven cancer progression involves upregulation of its own ligands such as CXCL1 and CXCL2 by potentiating NF-κB activation via EGFR-transactivated Akt signaling followed by accelerated ovarian cancer cell proliferation, migration and invasion." (PMID 24376747, 2013). "Finally, we investigated the effect of CXCL1 and CXCL2 in clinical ovarian cancer samples." (PMID 29703902, 2018). "For example, chemokine CXCL2 maintains cancer cell stemness and activates the ATR/CHK1 signaling pathway to promote platinum resistance in ovarian cancer." (PMID 40968783, 2026). "ITLN1, conversely, antagonizes tumor neovascularization and MDSC accumulation via IL-17D/CXCL2 axis modulation, thereby reshaping the immunosuppressive TME—a mechanism aligning with its prognostic significance in both CRC and ovarian cancer." (PMID 40145096, 2025). "High expression of CXCL2, CXCL10, and CXCL11 is correlated with favorable prognoses in ovarian cancer." (PMID 40689422, 2025). "Although CXCL2 and CXCL3 belong to the CXC chemokine family, their roles in the polarization of macrophages in ovarian cancer remain undefined." (PMID 41360767, 2025). "Studies have reported that the presence of Snail in ovarian cancer contributes to immunosuppression by up-regulating CXCL1 and CXCL2 expression which promotes recruitment of myeloid-derived suppressor cells (MDSCs)." (PMID 38935747, 2024). "For example, in the development of ovarian cancer, the mechanism underpinning the control of lncRNA ACTA2-AS1 on chemokine ligand 2 (CXCL2) by absorbing miRNA-532-5p as ceRNA." (PMID 35412951, 2022). "cDNA microarray data conducted by our group revealed overexpression of CXCL2 and CXCL8 in ovarian cancer (OC) microenvironment." (PMID 34038868, 2021). "Overexpression of GAB2 in ovarian cancer cells promotes tumour growth and angiogenesis by upregulating the expression of CXCL1, CXCL2 and CXCL8, which are IKKβ-dependent." (PMID 31895688, 2020). "In summary, CXCR2-driven ovarian cancer progression directly upregulates its own ligands such as CXCL1 and CXCL2." (PMID 29515768, 2018). "As in mouse MDSCs, MDSCs from human ovarian cancer ascitic fluid samples were attracted by CXCL1, CXCL2, and CXCL5, and a CXCR2 antagonist inhibited this migration." (PMID 29703902, 2018). "Ovarian cancer patients showed significant increases in both CXCL1 and CXCL2 compared to those in healthy donors." (PMID 29703902, 2018). "Suppression of GAB2 in all three ovarian cancer cell lines decreased the mRNA levels of CXCL1, CXCL2 and CXCL8." (PMID 26657155, 2016). "Taken together, these findings suggest that overexpression of GAB2 in ovarian cancer cells promotes tumor growth and angiogenesis by upregulating expression of CXCL1, CXCL2 and CXCL8 that is IKKβ-dependent." (PMID 26657155, 2016).